RNA5SP526 (RNA, 5S ribosomal pseudogene 526)
Gene: Ribosomal RNA gene on chromosome 17 (38,144,201 to 38,144,287, reverse strand). Ensembl gene ENSG00000274663.
Homologues: Orthologues: mouse Gm55958 (69% identical), mouse Gm56034 (67% identical), chimpanzee 5S_rRNA (66% identical), guinea pig 5S_rRNA (54% identical). Paralogues in human: 5S_rRNA (100% identical), RNA5SP172 (66% identical), RNA5S1 (62% identical), RNA5S10 (62% identical), RNA5S11 (62% identical), RNA5S12 (62% identical), RNA5S13 (62% identical), RNA5S14 (62% identical), RNA5S15 (62% identical), RNA5S16 (62% identical), RNA5S17 (62% identical), RNA5S2 (62% identical), and 25 more.